MMP2 (matrix metallopeptidase 2)
Diseases named in the same sentence as MMP2 in open-access papers (continued):
Sharing a sentence is not in itself a finding about the gene and the disease.
glioma (continued). "MMP-2 and MMP-9 are two important members, which play important roles in the invasion and malignancy of glioma cells." (PMID 23593320, 2013). "Studies have revealed that PI3K/Akt signaling pathway is activated in the invasion of gliomas and is involved in the regulation of VCAM-1 and MMP-2/9 expressions." (PMID 23593320, 2013). "MMPs are essential for proper ECM remodeling and invasion while MMP-2 and MMP-9 are known to be overexpressed in gliomas." (PMID 23533307, 2013). "Here, we investigated the effect of rSAA on the expression and activity of MMP-2 and MMP-9 in two human glioma cell lines, A172 and T98G, and the correlation with cell proliferation, migration, and invasion." (PMID 23533307, 2013). "In the central nervous system, membrane type MMP-1 (MT1-MMP) has a more important role than MMP-2 during ECM remodeling, migration, infiltration, and invasion of gliomas." (PMID 23304519, 2012). "Matrix Metalloproteinase (MMP) inhibition experiments and assays demonstrated that the glioma cells depended on MMP activity to invade, and suppression in motility correlated with downregulation of MMP-1 and MMP-2 levels." (PMID 21637818, 2011). "The expression of MMP-2 and MMP-9 in the glioma specimens was observed in the tumor cellular cytoplasm, the vascular endothelial cells and the basement membranes." (PMID 23554622, 2010). "In our lab, PLGA has been used to produce particles loaded with PEX, a fragment of matrix metalloproteinase (MMP)-2, or platelet factor 4 fragments (PF-4/CTF) for the delivery of these angiogenesis inhibitors to glioma bearing nude mice." (PMID 20932320, 2010). "The present study showed that MMI-166 reduced the activities of MMP-2 and MMP-9 and significantly inhibited the invasive and angiogenic activities of glioma cells in vitro and in vivo." (PMID 20587068, 2010). "In the low grading gliomas, quantitative analysis revealed the mean expression levels of MMP-2 and MMP-9 staining were 16.38±8.43% and 12.09±7.98%, respectively, compared to those of 60.47±21.45% and 41.03±14.00% in the high grading gliomas." (PMID 23554622, 2010). "Both the latent and active forms of MMP-2 and the latent form of MMP-9 were detected in the culture supernatant from glioma cells." (PMID 20587068, 2010). "In order for angiogenesis to progress extracellular matrix (ECM) degradation is necessary and the metalloproteinases 2 and 9 (MMP2 and MMP9) are highly expressed in gliomas." (PMID 19292920, 2009). "In order to distinguish the role of heparanase on cell invasion, MMP-2 and MMP-9, members of the MMP family that is also involved in glioma invasion, was measured using zymography assay and real-time PCR in both heparanase-overexpressing and control cells." (PMID 18647407, 2008). "In this study, we demonstrate for the first time that berberine sensitizes malignant glioma cells for As2O3-mediated suppression of migration and invasiveness likely via decreased PKC signaling and MMP-2 activation in the extracellular matrix." (PMID 18294404, 2008). "Consistent with our findings, previous reports in v-Src transformed fibroblasts and glioma cells supported a role for FAK in promoting increased MMP-2 gene expression." (PMID 18349846, 2008). "Based on the assumption that CHL is able to efficiently penetrate inside the cells, U-87 glioma cells were treated with different concentrations of CHL and the secretion of matrix metalloproteinase (MMP)-2 was monitored by zymography." (PMID 16566826, 2006). "Growth factors generally up-regulated MMP-2 and MMP-9 expression in the gliomas but were least effective in the meningioma; the effect being most prominent with TGF-β1 and TGF-β2 in all the cell lines." (PMID 10638966, 2000). "Therefore, we investigated the effects of Calanquinone A on MMP2 and MMP9 expression in glioma cells." (PMID 40759869, 2025).
glioma (continued). "Our findings demonstrate that CAPE, particularly under IFN-α or combined LPS + IFN-α stimulation, enhances MMP-2 secretion, indicating that CAPE may influence glioma invasiveness through modulation of ECM-remodeling enzymes." (PMID 41515435, 2025). "Among these, MMP2 and MMP9 are gelatinases that contribute to glioma progression." (PMID 40759869, 2025). "In gliomas, miR-383 targets insulin-like growth factor 1 receptor (IGF1R), leading to suppression of AKT signaling and downregulation of matrix metalloproteinase 2 (MMP2), thereby inhibiting glioma cell invasion." (PMID 38625593, 2025). "Furthermore, another promising theranostic strategy targets matrix metallopeptidase-2 (MMP2), overexpressed in many gliomas." (PMID 40806525, 2025). "Similarly, it has also been shown that the inhibition of MMP2 and MMP9 by EFEMP2 knockdown resulted in a reduction in glioma invasion." (PMID 39458959, 2024). "According to KEGG database and previous findings, wound healing assay was applied to assess the key apoptosis-related markers, including Bax and Bcl-2, and invasion-related protein, MMP2, for validation the anti-cancer effect and mechanism of ADRA2C drugs in glioma 33-36." (PMID 39308687, 2024). "Still only BMP2, MMP13, MMP2, LCK, MMP9, and AR have been reported to affect the glioma invasion." (PMID 39458959, 2024). "Additional support may be inferred from other findings in this study, where increased MMP-2 and MMP-9 levels under NF-κB regulation suggest that low NaF concentrations in U-87 glioma cells might promote adverse NF-κB activation." (PMID 39684484, 2024). "SLC39A1 could foster the MMP2/MMP9 expression and glioma cell proliferation and its expression is correlated to the pathological grade, IDH mutational status, and 1p19q co-deletion." (PMID 39012280, 2024). "Expression of MMP-2 and MMP-9 positively correlates with glioma grade." (PMID 38969910, 2024). "To explore the underlying molecular mechanisms, we examined whether EMT and MMP-2, which are recognized as important factors of glioma invasion 11, 12, were involved in IGFBP5-mediated promotion of glioma cell growth." (PMID 38164271, 2024). "Additionally, exposure to these exosomes reduced the expression of matrix metalloproteinase-2 (MMP-2), which promotes carcinogenesis, and, therefore, miR-584-5p was suggested to suppress the metastasis of glioma cells." (PMID 39200286, 2024). "Our results further demonstrated that isocuB could impede glioma cell proliferation and migration by inhibiting STAT3 to inhibit MMP2/9." (PMID 38835342, 2024). "Further, qRT-PCR and Western blot analysis showed CLEC19A overexpression could reduce the expression levels of PI3K, VEGFα, MMP2, and NF-κB and increase PTEN, TIMP3, RECK, and PDCD4 expression levels in glioma cell lines." (PMID 38167030, 2024). "ClTx was found to selectively bind to glioma cell-MMP-2, but not to normal glial cells, forming a ClTx-MMP-2 complex." (PMID 39361208, 2024). "In addition, we found that the expression levels of VEGFA, MMP2, and MMP9 were, unsurprisingly, downregulated after inhibition of AKT signaling, even in L1‐overexpressing glioma cells." (PMID 36708044, 2023). "Recently, it was demonstrated that inhibition of IGFBP2 in U251 cells in an orthotopic mouse model significantly reduces angiogenesis mimic formation and inhibition of tumor progression, and IGFBP2 stimulates glioma cell angiogenic mimicry formation via CD144 and MMP2 up-regulation." (PMID 38012763, 2023). "Further study has revealed that chlorotoxin could exclusively bind to the surface of glioma cells and show an anti-invasive effect due to interacting with MMP-2 isoforms, as the main CTX receptor, on the surface of glioma cells." (PMID 37070616, 2023).
glioma (continued). "Important factors expressed by TAMs in gliomas include TNF-ß, high levels of interleukins 6 and 10 (Il-6, Il-10), MMP2 and MMP9, and VEGF and VEGA, which collectively promote glioma proliferation and invasion, angiogenesis and suppression of T effector cell and NK cell activity." (PMID 38275375, 2023). "Moreover, rhSHH upregulates MMP-2 and MMP-9 expression and protein levels, while cyclopamine downregulates mRNA and protein concentrations in glioma U251 cells." (PMID 38069210, 2023). "Additionally, the expression of MMP-2 and MMP-9 was observed to be significantly higher in recurrent gliomas than in primary gliomas, and correlated with increased resistance to radiotherapy." (PMID 36675073, 2023). "From the literature, it is proposed that ClC-3 and MMP-2 form a protein complex that is targeted by the CTX-peptide, and this action is thought to inhibit glioma cell migration and invasion through the induction of endocytosis of the MMP-2/ClC-3 protein complex." (PMID 37444498, 2023). "Hence, CTX targeting MMP-2 has been widely investigated and proposed as one of the main molecular mechanisms for the development of CTX-based treatments for gliomas." (PMID 37444498, 2023). "Upon activation of pro-MMP2 in MMP2, MT1-MMP promotes the invasion of glioma cells." (PMID 35328780, 2022). "Additionally, IGFBP2 can promote the formation of angiogenic mimics by regulating the expression of CD144 and MMP2 in glioma as well as enhancing nuclear EGFR-STAT3 signaling, which can be used as a therapeutic target for glioma." (PMID 35992105, 2022). "We found that SCIN and MMP2/9 were upregulated in the primary glioma, SCIN had an excellent correlation with MMP2 and MMP9, and these proteins were closely related to the prognosis of a glioma." (PMID 36291348, 2022). "Western blot analysis demonstrated that the protein levels of LASS2 and TIMP2 were apparently elevated, accompanied by reductions in SPHK1, MMP2, and MMP9 protein levels, in glioma xenografts derived from U-87 MG-pLV-LASS2 cells compared with those derived from U-87 MG-pLV cells." (PMID 35517425, 2022). "In addition, tumor cells use aerobic glycolysis in energy metabolism despite adequate oxygenation; excess extracellular lactate enhances the expression of MMP-2 and integrin αvβ3 via high expression of TGF-β2, which enhances glioma cell migration." (PMID 35204054, 2022). "DKC1 could upregulate the expression of N-cadherin, MMP-2, HIF1A, CDK2, and cyclin E, and the glioma cells with DKC1 knockdown exhibited low motility." (PMID 36437949, 2022). "In addition, TGF-β2 induced the expression of matrix metalloprotease-2 (MMP2) and suppressed the expression of tissue inhibitors of metalloproteinases (TIMP)-2, which degraded the extracellular matrix to promote glioma invasion." (PMID 35600367, 2022). "The results verified that the protein expression of SCIN and MMP2/9 were upregulated significantly in glioma tissues compared with normal brain tissues and were higher in high-grade (Grade III–IV) gliomas than in a low-grade (Grade II) glioma." (PMID 36291348, 2022). "Moreover, MMP-2 and MMP-9 have a synergistic impact on the breakdown of endothelial basement membrane in gliomas and facilitate the release of ECM-bound VEGF." (PMID 35884733, 2022). "Indeed, downregulation of HIF-1α by siRNA decreases both the level of matrix metalloproteinase (MMP)-2 as well as the functions of MMP-2 and MMP-9 decreasing the mobility of glioma cell via the impaired invasion-related molecules." (PMID 35205167, 2022). "This study proposed that PRL-3, MMP2 and MT1-MMP cooperatively promote glioma invasion." (PMID 35098869, 2022). "Thus, it has been gradually accepted that MMP2 and MMP9 are candidate biomarkers for monitoring chemotherapy in high-grade glioma as well as indicating poor prognosis in glioma recurrence." (PMID 33889541, 2021).
glioma (continued). "Regarding thymol, treatment at concentrations of 100 and 200 μM induced a significant reduction in cell viability and inhibited the migration of glioma cells (C6 cell line) through phosphorylation of PKCα and ERK1/2, that resulted in decreased expression of MMP-9 and MMP-2." (PMID 34305611, 2021). "Among MMPs, MMP‐2 and MMP‐9 have been indicated as having an upregulated expression in glioma." (PMID 33300633, 2021). "In addition, the overexpression of LACTB can inhibit the expression of PCNA, MMP2, MMP9 and VEGF, which are believed to play an important role in the proliferation, invasion and angiogenesis of glioma cells." (PMID 33507917, 2021). "In addition, immunohistochemistry of intracranial glioma tissues further confirmed that CYB561D2 increased PD-L1, MMP2 (invasion marker) and Ki-67 (proliferation marker) in a STAT3-depedendt manner." (PMID 34372858, 2021). "For example, the expression of matrix metalloproteinase 2 (MMP-2) cleavage enzyme, MT1-MMP, has been positively correlated with increasing glioma malignancy grade, and GAM have also been shown to induce MMP-9 expression via release of transforming growth factor beta (TGF-β)." (PMID 34572134, 2021). "In gliomas, a downregulation of LACTB leads to an increase in cancer cell proliferation and angiogenesis, corresponding to a poor prognosis in patients, while its overexpression does the opposite by inhibiting PCNA, MMP2, MMP9, and VEGF, which are key regulators in glioma cell proliferation." (PMID 34361072, 2021). "DDR1 is highly expressed in pediatric high-grade gliomas as well as adult gliomas, irrespective of grades, where cells overexpressing the receptor show enhanced invasion and migration, likely as a result of activation of MMP2." (PMID 33673213, 2021). "Luo and coworkers have recently shown that STC1 levels directly correlate with those of matrix metalloproteinases (MMP)-2, MMP9, and vimentin in gliomas, and these authors hypothesized that STC1 augments the invasive capacities of glioma cells." (PMID 34394104, 2021). "Further, western blot was used to detect the changes of the expression of VM formation-related proteins MMP2, MMP9, and VE-cadherin in glioma cells after HNRNPD knockdown, we found that compared with HNRNPD(−)-NC group, the expression of the proteins decreased significantly in HNRNPD(−) group." (PMID 33542193, 2021). "The mRNA expression and RNASeq of matrix metalloproteinase 2 (MMP2) and matrix metalloproteinase 14 (MMP14) is presented for differing grades of glioma using the Gliovis data portal for visualization and analysis of brain tumor expression datasets to analyze data from the TCGA and the CCGA." (PMID 33919029, 2021). "Another lncRNA metastasis-associated lung adenocarcinoma transcript 1 (MALAT1) inhibits cell proliferation and invasion through the downregulation of extracellular signal-regulated kinase (ERK), matrix metalloproteinase 2 (MMP2) and MMP9 in U87 and U251 glioma cells and glioma nude mice models." (PMID 34202078, 2021). "Additionally, microglia-derived CCL5 triggers upregulation of MMP2 in glioma cells through calcium and Akt signaling, which in response promotes ECM degradation and invasiveness in glioma." (PMID 34503065, 2021). "It was reported that VM formation in glioma samples was related to the increased VEGF and MMP-2." (PMID 34434564, 2021). "CCK-8 and flow cytometry results show that SLC39A1 promotes proliferation of glioma cells and inhibits their apoptosis; RT-qPCR and western blot results show that SLC39A1 promotes the progression of glioma by increasing the expression level of MMP2\MMP9." (PMID 33292262, 2020). "miR-940 was also significantly downregulated in glioma samples and overexpression in cell lines U87 and LN229 dramatically decreased expression levels of mesenchymal markers, such as N-cadherin, Vimentin, Fibronectin, α-SMA, and MMP2." (PMID 33240194, 2020). "IKKε knockdown is involved in the decreased MMP2 and MMP9 production in glioma cells." (PMID 32064021, 2020).
glioma (continued). "Importantly, interference with CD147 expression significantly reduced the secretion and expression of MMP-2 and MMP-9, which reduced the proliferation of glioma cells induced by psychological stress." (PMID 33178600, 2020). "Kaji T showed that MMP-2 and MMP-9 were highly expressed in glioma cells." (PMID 33178600, 2020). "Likewise, in cultured glioma cells, THC exposure inhibited the expression of MMP-2 and reduced invasion, indicating that reduction in MMP-2 plays a fundamental part in THC-induced reduction of cell invasion." (PMID 32708138, 2020). "Moreover, MMP2 expression and secretion are FAK-dependent mechanisms, as already demonstrated in glioma cell lines." (PMID 31986121, 2020). "In summary, we discovered the molecular regulatory network in which SRSF10 facilitated circ-ATXN1 biogenesis and subsequently increased its binding with miR-526b-3p to inhibit the negative regulatory effect of miR-526b-3p on MMP2 and VEGFA in regulating glioma angiogenesis." (PMID 32600379, 2020). "Smaller diameter gliomas have been shown to have lower expression of MMP-2, whereas MMP-2 is highly expressed in larger diameter malignant gliomas, with a corresponding decrease in expression of a group of inhibitory proteins, tissue inhibitors of metalloproteinases (TIMPs)." (PMID 33322413, 2020). "Studies have shown that MMP2\MMP9 are zinc-dependent proteolytic enzymes involved in the remodeling and degradation of extracellular matrix (ECM) and can enhance the invasion and metastasis of glioma." (PMID 33292262, 2020). "Next, we explored whether the accumulation of MMPs in glioma was due to a transcriptional up-regulation of MMP1 and MMP2." (PMID 31846454, 2019). "In addition, CBX7 was found to regulate negatively migration and invasion via upregulation of E-cadherin and downregulation of matrix metalloproteinase (MMP)-2, MMP-9, and vimentin in glioma." (PMID 31709304, 2019). "In a study of glioma, it was found that SPOCK1 and SPOCK3 could inhibit MT1-MMP-mediated MMP2 activation and inhibit glioma cell invasion by binding to MT1-MMP." (PMID 31338255, 2019). "To corroborate these results, we undertook qPCRs experiments with RNA extracted from control and glioma larvae, which revealed no change in the transcription (mRNA levels) of MMP1 or MMP2 in glioma samples relative to the control." (PMID 31846454, 2019). "In contrast, high levels of SPOCK2 could abrogate this inhibition of MMP2 by SPOCK3 and increase the invasiveness of glioma cells." (PMID 31338255, 2019). "Down-regulation of PEBP1, also known as the Raf-1 kinase inhibitor protein (RKIP), is associated with glioma progression, and it has been demonstrated that RKIP, by inhibiting MMP-2 and MMP-9 expression, markedly reduces the ability of glioma cells to migrate and invade." (PMID 30845786, 2019). "C1q may activate the canonical Wnt/β-catenin signaling pathway, which increases MMP-2 and MMP-9 expression by glioma cells." (PMID 30208949, 2018). "Glioma cells are also able to activate toll-like receptor (TLR) signalling in the microglia, which results in MT1-MMP expression and subsequent activation of the pro-invasive MMP2 by GSC." (PMID 29300332, 2018). "The FITC-iCREKA was proved to have significantly higher cellular uptake in the glioma U87 cells in the presence of activated MMP-2 than that in absence of activated MMP-2 by cells fluorescence test in vitro." (PMID 29686590, 2018). "To test this possibility, we conducted PLA to determine whether NHE1 is closely located with MMP2, MMP9, or MT1-MMP in glioma cells." (PMID 30262908, 2018). "CTX has also been demonstrated to selectively and specifically act on matrix metalloproteinase (MMP)-2, which is expressed in glioma and other tumors, but is not present in normal brain tissues." (PMID 30486274, 2018).